MXRA5 (matrix remodeling associated 5)
Diseases named in the same sentence as MXRA5 in open-access papers (continued):
Sharing a sentence is not in itself a finding about the gene and the disease.
tumor (22 papers, 2009 to 2026). "Among the tumor-enriched GLYs, matrix-remodeling associated protein 5 (MXRA5) had the greatest statistical significance (p = 7.13 ×10−6)." (PMID 40032993, 2025). "The analysis showed that in GBM, MXRA5 expression closely correlated with M2 tumor-associated macrophage infiltration but had little correlation with M1 and Treg infiltration." (PMID 34211612, 2021). "We found that MXRA5 expression is highly correlated with immune checkpoint molecule expression levels and tumor-associated macrophage infiltration." (PMID 34211612, 2021). "The elevated MXRA5 was reported to be associated with tumor angiogenesis." (PMID 39149564, 2024). "The analysis showed that in GBM, MXRA5 closely positively correlated with M2 tumor-associated macrophage infiltration but had little correlation with M1 and Treg infiltration, which indicates that MXRA5 may play a role in tumor immunosuppression." (PMID 34211612, 2021). "The fact that mutations in MXRA5 may be associated with transition from e- to s- phenotype is further confirmed by the positive association we observed with the s-component percentage in the tumor." (PMID 32872534, 2020). "MXRA5 potentially aids tumor progression by enhancing cell proliferation, migration, and epithelial-mesenchymal transition, making it a viable therapeutic target for various tumors." (PMID 40688463, 2025). "The estimated daily tumor growth, in mm3 per day, was calculated (using the described formula) and results showed that aav-MXRA5-sh-S1 injection robustly inhibited priPC-1 xenograft growth in mice." (PMID 36828810, 2023). "The fresh tumor tissues were analyzed, we found that MXRA5 protein expression was significantly decreased in tissues of three ko-MXRA5 PANC1 xenografts, where p-Akt (Ser-473) and p-S6 were significantly inhibited." (PMID 36828810, 2023). "COL3A1, COL1A2, COL15A1, ASPN, and MXRA5 were higher expressed in tumor samples, while OGN was lower expressed." (PMID 32300359, 2020). "Of the 9 genes tested, 8 (THBS1, CYR61, CTGF, MXRA5, SPP1, LTBP2, TGFBR1 and COL11A1) were found by qRT-PCR to be significantly differentially expressed in tumor-associated fibroblasts, for a validation rate of 89%." (PMID 26575166, 2015). "Comprehensive immune profiling showed that high expression of F2R/MXRA5 was associated with an immunosuppressive microenvironment, exhibiting reduced infiltration of dendritic cells and macrophages, elevated TIDE scores, and decreased tumor purity." (PMID 41968212, 2026). "In addition, GEO dataset (GSE62452) showed that MXRA5 overexpression is positively correlated with higher tumor clinical pathological stage (Stage-I&II vs. Stage III & IV; P < 0.01)." (PMID 36828810, 2023). "This suggests that MXRA5 plays different roles in different tumours." (PMID 35292033, 2022). "Therefore, we hypothesized that MXRA5 is likely to promote the malignant progression of GBM by participating in the immunosuppression of the tumor microenvironment." (PMID 34211612, 2021). "RT-PCR results showed that the expression of FMOD, MXRA5 and RAB36 in tumor tissues of most patients was higher than that in paracancerous tissues." (PMID 39513108, 2024). "Functional assays demonstrated that two miRNAs acted as tumor-suppressive miRNAs in BC cells by targeting cell-cycle-related genes (e.g., TRIP13, CCNB1, RAD51, PSPH, CENPN, KPNA2, and MXRA5)." (PMID 39728605, 2024). "The most enriched glycoproteins in tumour ECM compared to non-tumour ECM included thrombospondin-2 (16.9-fold), MXRA5 (14.4-fold), peroxidasin (2.5-fold), thrombospondin-1 (2.5-fold), SPARC (2.3-fold), FRAS1 (2.3-fold) and tenascin-C (2.1-fold)." (PMID 37397358, 2023). "Through CGGA and TCGA transcriptome analysis, we found that the expression of MXRA5 was highly positively correlated with the expression of immune checkpoints, the immunosuppressive factor TGFB1, and tumor invasion markers." (PMID 34211612, 2021).
tumor (continued). "The MXRA5 protein is aberrantly expressed in non-small-cell lung carcinoma (NSCLC), and a high MXRA5 expression is correlated with tumor progression and overall survival, indicating its potential value as a novel therapeutic target for the treatment of NSCLC." (PMID 33065998, 2020). "Of these, 8 genes showed a significant decrease in expression in tumor samples with this deletion relative to tumors samples without this deletion: ARSD, ARSE, MXRA5, PRKX, LOC729137, NLGN4X, HDHD1A, and STS." (PMID 19419571, 2009).
kidney disease (2 papers, 2017 to 2024). "Additional studies will be required to determine the clinical relevance of MXRA5 as a biomarker in renal disease as well as to better characterize the molecular determinants of MXRA5 action, including the search for receptors." (PMID 27599751, 2017). "In conclusion, MXRA5 is a molecule involved in the regulation of important biological processes, such as inflammation and fibrosis, during kidney disease." (PMID 27599751, 2017). "Previous studies have shown that MXRA5 exerts anti-fibrotic and anti-inflammatory effects in kidney disease; therefore, MXRA5 may serve as a compensatory mechanism in the calcification process by promote ECM production." (PMID 39749331, 2024). "Previous studies have shown that MXRA5 has anti-fibrotic and anti-inflammatory effects in kidney disease, so MXRA5 may be a compensatory mechanism in the calcification process to promote the production of ECM." (PMID 39749331, 2024). "Among the potential explanations for this discrepancy, we should now add the lack of MXRA5 in rats and mice used as models of kidney disease, while this potentially nephroprotective molecule is present in humans and down‐regulated by VDR activators." (PMID 27599751, 2017). "However, the fact that mice and rats do not express MXRA5 will complicate the development of preclinical models to address its in vivo function in kidney disease." (PMID 27599751, 2017).
cardiovascular diseases (1 paper, 2024). "Understanding the exact mechanism by which MXRA5 contributes to cardiovascular disease, specifically CAVD, is critical for the development of targeted therapies." (PMID 39749331, 2024). "Understanding the exact mechanism by which MXRA5 contributes to cardiovascular diseases, particularly CAVD, is crucial for the development of targeted therapies." (PMID 39749331, 2024).
inflammation (1 paper, 2020). Aberrant reaction of the microcirculation characterized by movement of fluid and leukocytes from the blood into extravascular tissues. "Matrix remodeling-associated protein 5 (MXRA5) is a protein of unknown function belonging to the MXRA gene family that mediates kidney inflammation or fibrosis." (PMID 32984216, 2020).
MXRA5 also shares sentences with these, for which no sentence is quoted: acute myeloid leukemia (1 paper); aortic valve stenosis (1); bladder cancer (1); clear cell sarcoma (1); colon cancers (1); cyst (1); diabetes (1); diabetic nephropathy (1); endometrial cancer (1); focal segmental glomerulosclerosis (1); gallbladder carcinoma (1); gastric cancer (1); glaucoma (1); glomerulonephritis (1); kidney inflammation (1); liposarcoma (1); lung fibrosis (1); lupus nephritis (1); metastatic tumors (1); multiple myeloma (1); nephrosclerosis (1); renal cell carcinoma (1); schizophrenia (1).